TIE1 (tyrosine kinase with immunoglobulin like and EGF like domains 1)
Diseases named in the same sentence as TIE1 in open-access papers (continued):
Sharing a sentence is not in itself a finding about the gene and the disease.
cancer (27 papers, 2010 to 2025). A tumor composed of atypical neoplastic, often pleomorphic cells that invade other tissues. "Recent studies have also shown that elevated Tie1 expression is intimately associated with atherosclerosis and the stemness of cancer stem cells 12, 14-17." (PMID 32174801, 2020). "To obtain insights into associations of Tie1 with tumorigenesis, we first explored Tie1 expression patterns in different types of cancer using Oncomine, a clinical database of human cancer." (PMID 28464467, 2017). "In recent years, increased TIE-1 expression has been observed in many types of cancers; however, the biological significance and underlying mechanisms remain unknown." (PMID 32604863, 2020). "We found that Tie1 expression was associated with cancer stemness properties of the cells." (PMID 28464467, 2017). "In primary tumors, TIE1 undergoes cleavage and promotes cancer cell survival by activating the AKT–p70S6K signaling pathway." (PMID 41235901, 2025). "Collectively, these findings strongly support the notion that TIE1 serves as a critical regulatory factor in various cancers including GC, and it is highly expressed in GC." (PMID 38706903, 2024). "In this study, evidence from multiple databases revealed that TIE1 exhibited significant overexpression in various cancer types, including GC." (PMID 38706903, 2024). "According to GO and KEGG enrichment analyses, TIE1 was enriched in signal pathways related to the occurrence, invasion, and migration of malignant tumors (i.e., PI3K-Akt signaling pathway, Calcium signaling pathway, etc.)." (PMID 38706903, 2024). "PECAM1 expression was closely associated with other well-established TAE markers such as CDH5 (R = 0.94) and TIE1 (R = 0.93) in cancer str of the CRC tumors." (PMID 38557819, 2024). "To establish the role of Tie1 in cancer stem cell, we performed limiting dilution tumorigenicity assay, further found that A549 cells transfected with sh-Tie1 formed smaller subcutaneous tumors." (PMID 33461544, 2021). "As tie1 is also upregulated in intratumoral vasculature, its deletion on ECs successfully produced a potent anti-angiogenic effect in different cancers." (PMID 33469537, 2020). "In fact, EC-specific deletion of tie1 in lung carcinoma and melanoma mouse models resulted in delayed cancer growth, predominantly in late-stage tumors." (PMID 33469537, 2020). "Here, to obtain insights into Tie1 functions in tumorigenesis, we explored Tie1 expression patterns in different types of cancer." (PMID 28464467, 2017). "Despite having detected a small proportion of Tie1‐positive cancer cells in in vivo tumors, Tie1‐positive HT29 cells were essentially absent from in vitro cultures." (PMID 28464467, 2017). "Our results provide a novel insight into Tie1 function in tumorigenesis and suggest clinical applications to target cancer stem cells." (PMID 28464467, 2017). "In these studies, Tie1 expression was observed in cancer cells themselves, as confirmed by immunohistochemistry." (PMID 28464467, 2017). "When we become capable of expanding these Tie1‐positive cancer cells either in vitro or in vivo, their biological significance in malignant progression will be analyzed." (PMID 28464467, 2017). "In this respect, we showed that sphere‐formation culture enabled cancer cells to maintain a population of Tie1‐positive CSCs in vitro." (PMID 28464467, 2017). "We found increased expression of two 'endurance exercise'-activated genes, CaMKIIβ and TIE1, across different muscle groups in human cancer cachexia." (PMID 20193046, 2010). "In this study, we investigated the expression of TIE1 in pan-cancer using the TIMER database." (PMID 38706903, 2024). "The involvement of Tie1 in the stemness of cancer cells has also been noted in another study." (PMID 33461544, 2021).
cancer (continued). "The authors of this study identified several receptor tyrosine-protein kinases (RTK) in the drug resistance of NSCLC cells, including ERRB4, KIT, and Tie1, and suggested that the inhibition of RTKs may sensitize cancer cells to paclitaxel." (PMID 33461544, 2021). "The exact functions of TIE1 in cancer remain unknown, but given the contributions of TIE1 and -2 to angiogenesis, their role in hypoxic tissue seems especially relevant." (PMID 33105540, 2020). "Another potential angiogenic target for cancer treatment is tie1." (PMID 33469537, 2020). "Having shown that a small population of cancer cells expresses Tie1 in vivo, we next assessed whether Tie1 expression in cancer cells in normal two‐dimensional cultures (i.e., regular in vitro conditions) can be detected." (PMID 28464467, 2017). "Also in this case three genes (CDH5, CXorf36, and TIE1) were present in the final cluster in all six cancer sets." (PMID 27809802, 2016). "Biological validation of TIE1 and CaMKIIβ expression in an independent clinical cohort across distinct muscle groups, along with supportive network analysis, provides weight to the claim that these are useful markers of cancer cachexia in humans." (PMID 20193046, 2010). "Furthermore, overexpression of Tie-1 in ECs is capable of inducing an inflammatory response and it might pose a target for anti-angiogenesis treatments in cancer." (PMID 31979004, 2020). "Indeed, a recent study showed that treatment with a TIE1 function-blocking antibody in a presurgical neoadjuvant setting suppressed distant organ metastasis, suggesting TIE1 as a promising therapeutic target in cancer treatment." (PMID 33217955, 2020). "Besides, Tie1-positive cells show cancer stemness properties." (PMID 31579438, 2019). "Therefore, we concluded that Tie1 expression is involved in the in vivo growth of cancer." (PMID 28464467, 2017). "Moreover, coculture of cancer cells with cancer‐associated fibroblasts also failed to maintain Tie1 expression in cancer cells." (PMID 28464467, 2017). "Merck’s angiogenic signature was selected as genes co-expressed with known angiogenic genes, KDR, TIE1, TEK, and CD34, in public pan-cancer genomic datasets." (PMID 39835481, 2025). "We predicted the tie1 and tie2 fusion transcript of NTN1 and its receptor from the TumorFusions Database28 in TCGA cancers." (PMID 41407823, 2025). "The expression level of Tie-2 showed a weak, but significant correlation with Ang-2 PP (r = 0.3, p = 0.012) and moderate correlation with Tie-1 IRS and PP (r = 0.5, p <0.001; r = 0.4, p <0.001) in primary cancer of the whole studied population." (PMID 33151982, 2020). "However, it is not clear whether Tie1 expression is a cause or result of acquisition of malignancy and/or cancer stemness properties." (PMID 28464467, 2017). "We observed that Tie1‐positive cancer cells remained after eliminating CD31+ endothelial cells and CD45+ hematopoietic cells which are known to express Tie1." (PMID 28464467, 2017). "The resulting activation of HIF-1 in these cancers leads to the transcriptional induction, not only of VEGF and VEGFRs, but also endothelin-1, angiopoietins, and angiopoietin receptors (Tie-1 and -2)." (PMID 25549350, 2014). "The abundance of genes related to vascular stability (CDH5, CLDN5, TIE1, JAM2, TEK) indicated that the group with a lower cholesterol score had higher vascular stability, while low vascular stability often promotes cancer growth." (PMID 38023262, 2023). "Xu and colleagues showed that LECT2/TIE-1 signaling pathway promotes liver fibrogenesis; however, the significance of LECT2/TIE-1 in cancer is still not clear." (PMID 32604863, 2020). "Elevated expression of Tie1 has been detected in different types of cancer and has a negative correlation with clinical outcome." (PMID 31579438, 2019). "Tie1 expression did not influence cancer cell proliferation in regular in vitro cultures, but significantly affected malignant growth of transplanted tumors in vivo." (PMID 28464467, 2017).
cancer (continued). "Recent studies suggest enhanced expression of Tie1 in several types of cancer and negative correlations between Tie1 levels and clinical outcome." (PMID 28464467, 2017). "Notably, TIE1, KIT, NTRK1, FGFR3, CSF1R, and INSRR were shared by both cancers." (PMID 34944663, 2021). "However, ANGPTL proteins do not bind to the ANGPT receptors, TIE1 and TIE2, and exhibit a plethora of functional roles, including the regulation of lipid and glucose metabolism, inflammation, and cancer." (PMID 26761211, 2016).
infection (5 papers, 2018 to 2022). The state of being infected such as from the introduction of a foreign agent such as serum, vaccine, antigenic substance or organism. "Remarkably, deletion of both tie1 and tie2 in a Δvprh/Δhns1 background (Δvprh/Δhns1/Δtie1/Δtie2) completely abolished the cell death and IL-1β secretion observed upon infection of BMDMs with the Δvprh/Δhns1 strain, without affecting TNFα secretion." (PMID 36155655, 2022). "While the Tie1/Tie2 heterodimeric complex enables both Ang1 and Ang2 to function as Tie2 agonists, in the presence of an infection or inflammation ECs shed the Tie1 ectodomain, and Ang2 binding results in Tie2 antagonism." (PMID 29740443, 2018).
adenocarcinoma (2 papers, 2009 to 2021). A common cancer characterized by the presence of malignant glandular cells. "In NSCLC, a female group of patients with adenocarcinoma and high expression of Tie1 had lower overall survival than those with a low expression of Tie1." (PMID 33461544, 2021). "Note, in the context of angiogenesis we found angiopoietin 1 (Angpt1) and tyrosine kinase with immunoglobulin and epidermal growth factor homology domains (TIE1) also down regulated in adenocarcinoma." (PMID 19812696, 2009).
TIE1 also shares sentences with these, for which no sentence is quoted: Sepsis (3 papers); Breast (2); cardiovascular disease (2); COVID-19 (2); hepatocellular carcinoma (2); lung carcinoma (2); prostate carcinoma (2); acute myeloid leukemia (1); anemia (1); bladder carcinoma (1); brain disorder (1); cholangitis (1); Cirrhosis (1); demyelination (1); developmental delays (1); diabetic retinopathy (1); hemangioma (1); hydrops fetalis (1); Hypercholesterolemia (1); Intellectual disability (1); ischemic cardiomyopathy (1); kidney chromophobe (1); liver disease (1); lung adenocarcinoma (1); lung squamous cell carcinoma (1); lymphatic malformation (1); Motor delay (1); nasopharyngeal carcinoma (1); non-small cell lung carcinoma (1); Oedema (1).
A further 12 diseases each share a sentence with TIE1 in 1 paper.